SPP1 (secreted phosphoprotein 1)
Diseases named in the same sentence as SPP1 in open-access papers (continued):
Sharing a sentence is not in itself a finding about the gene and the disease.
gastric cancer (continued). "Participating in tumorigenesis and metastasis, SPP1 is overexpressed in a variety of malignancies, including lung adenocarcinoma and gastric cancer." (PMID 31485443, 2019). "SPP1/OPN has also been reported to be overexpressed in gastric cancers and increasing levels have been detected with progression of disease." (PMID 21092330, 2010). "Our study identified a potential stromal immunosuppressive barrier in gastric cancer, driven by Macro_SPP1/C1QC macrophages and CD8_Tex_C1 T cells, which may contribute to immune dysfunction and therapy resistance." (PMID 40740771, 2025). "SPP1 not only plays a crucial role in general age-related conditions but also engages with immune cells in cancer, influencing the immune microenvironment and impacting the progression of gastric cancer and pancreatic cancer." (PMID 38248779, 2024). "We aimed to investigate the involvement of SPP1 + TAMs in the metastasis of gastric cancer." (PMID 38365757, 2024). "The results showed that the expression of SPP1 was significantly reduced in gastric cancer cells." (PMID 37670969, 2023). "Furthermore, the Transwell cell migration assay indicated that suppressing SPP1 expression markedly restrained the metastatic ability of gastric cancer cells." (PMID 37889539, 2023). "We then examined SPP1 expression in gastric cancer patients using the TCGA database." (PMID 37670969, 2023). "Briefly, our findings further suggest that SPP1 may serve as an auxiliary biomarker for the qualitative assessment of disease severity and help to identify the clinical outcomes of gastric cancer patients." (PMID 36612160, 2022). "Our findings demonstrated that type I collagen promoted TIC-like phenotypes and chemoresistance through ITGB1/YBX1/SPP1/NF-κB pathway, which may provide novel insights into gastric cancer therapy." (PMID 34758833, 2021). "This indicates that ITGB1 might participate in gastric cancer progression through YBX1/SPP1 signaling." (PMID 34758833, 2021). "Moreover, suppression of YBX1 or SPP1 suppressed the activation of NF-κB in gastric cancer cells cultured in 3D gels, indicating that 3D collagen culture upregulated NF-κB expression through YBX1/SPP1 signaling." (PMID 34758833, 2021). "Furthermore, SPP1 expression was significantly lower in gastric tumor tissue than that in normal tissue, and treatment with specific SPP1 siRNA showed increased cell migration and invasion in gastric cancer." (PMID 34357010, 2021). "Therefore, we confirmed that 3D collagen gels stimulate elevated expression of YBX1 and SPP1 through ITGB1 in gastric cancer." (PMID 34758833, 2021). "Previous data also showed that targeting SPP1 could inhibit gastric cancer cell epithelial–mesenchymal transition through inhibition of the PI3K/AKT signaling pathway." (PMID 32849813, 2020). "In fact, downregulation of SPP1 in gastric cancer tissues enhanced metastasis, suggesting that SPP1 expression may serve as a prognostic marker in gastric cancer that correlates with patient’s survival." (PMID 27800303, 2016). "Besides, it has been found that the suppression of neutrophil polarization-related genes and the activation of the immune checkpoint SPP1 could promote lymphatic metastasis in gastric cancer." (PMID 41316282, 2025). "High CD44 expression has been observed in gastric cancer stem cells, and SPP1-expressing TAMs correlated with a worse clinical outcome in gastric cancer, suggesting the SPP1/CD44 axis may be associated with stemness properties and resistance to anticancer therapies." (PMID 38521868, 2024). "Nonetheless, the involvement of SPP1 + TAMs in the metastasis of gastric cancer remains unclear." (PMID 38365757, 2024). "In addition to malignant cells, abnormal neutrophil polarization and maturation and activation of the immune checkpoint SPP1 might contribute to LN metastasis of gastric cancer." (PMID 37612741, 2023). "We further confirmed whether there was HOXC8-mediated SPP1 expression in gastric cancer cells." (PMID 37670969, 2023).
gastric cancer (continued). "Thus, we sought to verify whether YBX1/SPP1 mediated gastric cancer development through NF-κB signaling." (PMID 34758833, 2021). "In gastric cancer, YBX1 upregulates the expression of SPP1, promoting gastric tumor-initiating cells through the ITGB1/YBX1/SPP1/NF-κB signaling pathway." (PMID 40799245, 2025). "However, the involvement of SPP1 + TAMs in gastric cancer metastases remains unclear." (PMID 38365757, 2024). "CXCR4, SPP1, CXCL1, MMP9, and TIMP1 were up-regulated and NFE2L2 was down-regulated in gastric cancer cell lines compared with control." (PMID 38221932, 2024). "We found that SPP1 expression was significantly increased in advanced-stage gastric cancer (AJCC TNM stages III–IV) compared with early-stage gastric cancer (AJCC TNM stages I-II) in our GC cohorts." (PMID 36612160, 2022). "Our results showed that the abnormal expression of FN1, TIMP1, SPP1, APOE, and VCAN influenced the prognosis of patients with gastric cancer." (PMID 33015179, 2020). "The results showed that FN1, TIMP1, SPP1, APOE, and VCAN were related to OS in gastric cancer patients (p < 0.01)." (PMID 33015179, 2020). "Silencing SPP1 can inhibit the proliferation, invasion, migration, and the EMT process of gastric cancer cells by inhibiting the PI3K/AKT signaling pathway and promote the apoptosis of gastric cancer cells." (PMID 36688087, 2023). "Moreover, the MSLN, SPP1, THBS2, SPARC, FN1, IGFBP7, VCAN were up-regulated in gastric carcinoma samples, while FGA was down-regulated." (PMID 36842141, 2023). "The results of immunohistochemistry showed that the protein expression levels of RBP7, DES, SPP1, VIP, and PRKCG in gastric cancer tissues were higher than those in normal tissues, while PNOC, TNFRSF12A, and TUBB3 proteins are less expressed in gastric cancer tissues than normal tissues." (PMID 35174205, 2022). "Interestingly, the results of IHC revealed that there was a spatial co-expression pattern of SPP1+ macrophages and CD44+ epithelial cells in gastric cancer specimens, providing evidence for the crosstalk between these two cell types." (PMID 36612160, 2022). "Meanwhile, 3D cultured YBX1/SPP1 silenced gastric cancer cells showed a weakened ability to form colonies as well as diminished chemoresistance, indicating that 3D collagen promotes the TIC phenotype through YBX1 and SPP1." (PMID 34758833, 2021). "Data also showed that high expressions of fibronectin 1 (FN1), the tissue inhibitor of metalloproteinases 1 (TIMP1), secreted phosphoprotein 1 (SPP1), apolipoprotein E (APOE), and versican (VCAN) were related to a poor overall survival in gastric cancer patients." (PMID 33015179, 2020). "Furthermore, five of them (FN1, TIMP1, SPP1, APOE, and VCAN) were found to be related to gastric cancer." (PMID 33015179, 2020). "SPP1/OPN level were also higher in gastric cancer patients compared to the non-malignant group but was borderline significant (p = 0.05)." (PMID 21092330, 2010). "In contrast with previous reports, we also confirmed that the ITGB1/YBX1/SPP1/NF-κB signaling axis is correlated with drug resistance development in gastric cancer, and blockade of ITGB1/NF-κB signaling led to improved anticancer effects in a subcutaneous gastric cancer mouse model." (PMID 34758833, 2021). "We performed Quantitative Real-time PCR (qPCR) on 6 up-regulated genes (COL1A, BGN, SPP1, MELK, IGFBP4, SPARC) and 4 down-regulated genes (PGC, SST, MT1X, S100P) to verify our data in gastric cancer tissues (Tumor) and noncancerous tissues (Normal)." (PMID 25928635, 2015).
liver cancer (71 papers, 2013 to 2025). An epithelial or non-epithelial malignant neoplasm that arises from the liver. "Particularly, several key genes, such as SLC27A5, IGF2, EFNA3, DCAF4L2, and SPP1, have been demonstrated to be associated with liver cancer." (PMID 39628446, 2024). "SPP1, with inference value of 129.66 from the gene-disease association dataset, is regarded as potential drug targets for the liver cancer treatment." (PMID 35452485, 2022). "Previous studies reported that SPP1+fibroblasts caused platinum resistance in liver cancer 31, in our study, we found that E0 interacted intensively with fibroblasts through the SPP1 signalling pathway, revealing that E0 induced cisplatin resistance through fibroblasts." (PMID 38817863, 2024). "It is suggested that ITGAV and SPP1 may be considered as potential diagnostic biomarkers and therapeutic targets for liver cancer." (PMID 38374893, 2024). "However, SPP1 expression was strongly linked to tumor progression and liver cancer in liver tissue from Caucasian patients with liver cancer (HCC)." (PMID 38068980, 2023). "This down-regulation may be caused by down-regulation of SPP1 which was shown to increase the synthesis of the CD44 variant CD44v6 in liver cancer cells." (PMID 31882946, 2019). "The enrichment of SPP1+ TAMs in liver cancer mirrors their prominence in other malignancies, yet their role in this context appears to be particularly intricate." (PMID 40395129, 2025). "Preclinical studies demonstrated that targeting this niche, either through SPP1 blockade or macrophages-specific Spp1 deletion, improved anti-PD-1 response in murine liver cancer models." (PMID 40507339, 2025). "In liver cancer, SPP1+ TAMs emerge as highly specialised components of the tumour microenvironment, shaped by metabolic cues, spatial positioning, and possibly their developmental trajectory." (PMID 40395129, 2025). "A particularly intriguing aspect of SPP1+ TAMs in liver cancer is their terminally differentiated state and their dependency on PPARγ, a transcription factor known for its role in M2‐like macrophage polarisation and adipogenesis." (PMID 40395129, 2025). "In preclinical models, blocking SPP1 or specifically deleting Spp1 in macrophages enhanced the effectiveness of anti‐PD‐1 treatment in mouse liver cancer, resulting in reduced CAFs infiltration and increased cytotoxic T‐cell infiltration." (PMID 39924620, 2025). "The results of survival analysis indicated that the SPP1 gene can serve as a prognostic marker for liver cancer (p = 0.0241)." (PMID 39635536, 2024). "The RT-qPCR experiment was applied to further analyze the expression patterns of 3 key genes (COMP, ITGAV, and SPP1) in liver cancer patients who relapsed after 3 and 6 months." (PMID 38374893, 2024). "By integrating bulk RNA-seq with scRNA-seq analyses, we pinpointed the pivotal role of SPP1+ macrophages in modulating TIME in liver cancer and demonstrated the inhibition effects of SPP1 in HCC-TAMs." (PMID 39691723, 2024). "They further demonstrated that inhibition of SPP1 or macrophage-specific deletion of SPP1 in mice led to enhanced efficacy of anti-PD-1 treatment in liver cancer." (PMID 38064127, 2024). "Based on 4 genes (COMP, SPP1, COL4A2, and ITGAV) in the pathway of integrin cell surface interactions, a risk score model for prognosis of liver cancer was constructed." (PMID 38374893, 2024). "In pathway of integrin cell surface interactions, COL4A2, COMP, ITGAV, and SPP1 were used to perform LASSO Cox regression analysis to construct the prediction model of the overall survival rate of liver cancer patients in the TCGA database." (PMID 38374893, 2024). "In conclusion, our findings indicate that DAB2+ and SPP1+ macrophages are the dominant TAMs in liver cancer." (PMID 39239526, 2024). "In order to further verify the relationship between SPP1 expression and immune infiltration, an analysis of immune cell correlation in human liver cancer was conducted." (PMID 39635536, 2024).
liver cancer (continued). "The mRNA expression levels of COL4A2, COMP, ITGAV, and SPP1 were significantly increased in liver cancer tissues." (PMID 38374893, 2024). "The findings indicate that DAB2+ / SPP1+ TAMs are the dominant TAMs in liver cancer, and SPP1+ TAMs have been reported to be involved in the pro-tumor microenvironment in several studies 15, 56, 71-73." (PMID 39239526, 2024). "In liver cancer, SPP1-positive macrophages had a specific interaction with the fibroblast-associated TME." (PMID 38067407, 2023). "Preclinically, blockade of SPP1 or macrophage-specific deletion of Spp1 in mice led to enhanced efficacy of anti-PD-1 treatment in mouse liver cancer, accompanied by reduced CAF infiltration and increased cytotoxic T-cell infiltration." (PMID 37612741, 2023). "The expression of SPP1 in liver cancer patients was positively correlated with the immune score (R = 0.26, p = 3.1e-07) and stromal score (R = 0.12, p = 0.021)." (PMID 37097499, 2023). "Differential analysis of TAMs showed that SPP1, well known for its oncogenic role in liver cancer, was remarkably upregulated following ICB therapy." (PMID 35558087, 2022). "We used an orthotopic model in immune-competent mice with Hepa1–6 liver cancer cells and Hepa1–6 liver cancer cells overexpressing SPP1 (Hepa1–6spp1)." (PMID 35432310, 2022). "For further experimental validation, we knocked down SPP1 expression via siRNA in MHCC97H liver cancer cells and then applied NET stimulation." (PMID 35432310, 2022). "To confirm our analysis results, we used liver cancer tissues and para-cancer tissues to verify the expression of SPP1 with ELISA and qRT-PCR experiment." (PMID 35067176, 2022). "These can be used as markers for liver cancer diagnosis, among which FOBS and SPP1 genes can also be used as prognostic markers of liver cancer." (PMID 34238253, 2021). "Six genes (BIRC5, CACYBP, NR0B1, RAET1E, SPINK5, SPP1) were up-regulated in the liver cancer tissues compared to the normal tissues in the TCGA HCC dataset, and S100A8 was downregulated." (PMID 33568167, 2021). "As a result, only the FOSB and SPP1 genes are suitable for use as prognostic biomarkers of liver cancer, where the FOSB is a low-risk gene while the SPP1 is a high-risk gene." (PMID 34238253, 2021). "We found that SPP1 was upregulated in breast, bladder, colorectal, head and neck, liver cancer, lung, and esophageal cancers, whereas decreased in kidney cancer and sarcoma (p < 0.05)." (PMID 31849319, 2019). "In liver cancer, SPP1 may be involved in the regulation of immune response through several signaling pathways, such as the NF-κB signaling pathway, Th17 cell differentiation, and HIF-1, thus promoting the progression of the disease." (PMID 38726780, 2025). "Meanwhile, a recent study revealed that conditionally knocking out Spp1 in macrophages resulted in slower tumor growth rate and increased efficacy of ICI treatment in mouse model of liver cancer, highlighting the important role of Spp1+ TAMs in immunotherapy response." (PMID 40312419, 2025). "Notably, SPP1, a well-documented oncogene in liver cancer, was significantly downregulated in macrophages after GCP therapy, in contrast to the upregulation following ICB monotherapy reported previously." (PMID 41409288, 2025). "The authors showed that the tumor immune barrier created by SPP1+ macrophages interacting with CAFs hinders immune infiltration, and targeting the SPP1 improved the efficacy of anti-PD-1 therapy in the murine model of liver cancer." (PMID 38455762, 2024). "SPP1 has been regarded as a preclinical target for liver cancer treatment." (PMID 38374893, 2024). "Moreover, we detected SPP1 expression in M0 macrophages, tumor cells (breast, lung and liver cancer) and TAM by ELISA in vitro." (PMID 38648200, 2024). "The liver cancer survival rate was linked to ESR1, SPP1, and FOSB gene expression." (PMID 38726411, 2024).
liver cancer (continued). "In addition, ROC analysis showed that ITGAV, SPP1, COL4A2, and COMP had a potential diagnostic value for liver cancer patients." (PMID 38374893, 2024). "The risk score model constructed by genes (COMP, SPP1, COL4A2, and ITGAV) in the pathway of integrin cell surface interactions may be used to predict survival in liver cancer patients." (PMID 38374893, 2024). "It is indicated that the association between ITGAV, SPP1, COL4A2, COMP, and immune cells may be involved in the progression of liver cancer." (PMID 38374893, 2024). "Previous studies have indicated that Spp1 plays an important role in liver cancer." (PMID 38706319, 2024). "COL4A2 and SPP1 were significantly upregulated in liver cancer tissues." (PMID 38374893, 2024). "The model of SPP1 combined with centromere protein A (CENPA), melanoma-associated antigen family member B6 (MAGEB6), and homeobox D9 (HOXD9) can predict the overall survival in liver cancer patients." (PMID 38374893, 2024). "Blocking SPP1 expression in mice with spontaneous liver cancer increased the infiltration of T lymphocytes into tumors, suggesting that targeting SPP1 could enhance the effect of anti-PD-1 immunotherapy." (PMID 37896221, 2023). "Therefore, changes in the expression levels of ESR1, FOBS and SPP1 genes in liver cancer inhibited all three pathways." (PMID 34238253, 2021). "However, although SPP1+ TAMs have been generally correlated to a poorer prognosis and higher aggressiveness in many tumours, different behaviours from this macrophage population have been observed in the context of liver cancer, possibly indicating specific, yet uncovered functions of SPP1+ TAMs." (PMID 40395129, 2025). "However, the role of SPP1 in liver cancer warrants further investigation." (PMID 37097499, 2023). "Furthermore, an investigation was carried out to examine the relationship between SPP1 expression and immune subtypes, overall survival rate, staging, and grading of liver cancer, aiming to elucidate the connection between SPP1 expression and the prognosis as well as the progression of liver cancer." (PMID 39635536, 2024). "In our study, the expression trend of SPP1 and CSF1 in HCC was consistent, which was verified using liver cancer cells in vitro." (PMID 37097499, 2023). "To further investigate the mRNA expression levels of SPP1 and CSF1 in different liver cancer samples from the TCGA database, we performed a subgroup analysis using the UALCAN database." (PMID 37097499, 2023). "The expression levels of MYBL2, SPP1, CTSV and EPO were remarkably increased in liver cancer cells compared with normal liver cells, while the expression level of CYP2C9 was significantly decreased (p < 0.05)." (PMID 36650832, 2023). "In liver cancer, as reported in our previous work and confirmed by others, NETs promote MHCC97H cell invasion in a Transwell assay; however, SPP1 knockdown abrogated the invasion-promoting effect of NETs." (PMID 35432310, 2022). "In summary, seven of the genes (VEGFA, CTNNB1, SPP1, PPARG, RAC1, HSP90AA1, and LGALS3) were highly unregulated in patients with liver cancer." (PMID 35069936, 2022). "The results showed that among these Hub Genes, the expression levels of ESR1, SPP1 and FOSB genes was closely related to the survival time of liver cancer patients, with statistically significant differences (p < 0.05)." (PMID 34238253, 2021). "In liver cancer, the ESR1 gene is a low expression gene, while the SPP1 gene is a high expression gene." (PMID 34238253, 2021). "Among these, the expression levels of ESR1,SPP1 and FOSB genes were closely related to the survival time of liver cancer patients." (PMID 34238253, 2021).